FBXW7 (F-box and WD repeat domain containing 7)
Diseases named in the same sentence as FBXW7 in open-access papers (continued):
Sharing a sentence is not in itself a finding about the gene and the disease.
tumor (continued). "We previously identified the Fbxw7 gene (also known as hCDC4, Fbw7 and hAGO) as a tumor suppressor gene for radiation-induced lymphoma." (PMID 22348067, 2012). "In mice, the FBXW7 locus is required for viability but Fbxw7+/− heterozygotes exhibit increased incidence of tumor formation relative to wildtype animals." (PMID 23082202, 2012). "It has been reported that monoallelic deletion of Fbxw7 in different tumor systems, in human and mouse, is a frequent event during cancer progression, and that Fbxw7 acts as a haploinsufficient tumor suppressor gene." (PMID 22348067, 2012). "The tumor suppressor function of Fbxw7/hCdc4 is further underscored by frequent deletions of its locus at chromosome 4q31, occurring in more than 30% of all neoplasms." (PMID 21122106, 2010). "Semi-quantitative RT-PCR analysis of the different FBXW7/hCDC4 isoforms revealed substantial differential expression of the FBXW7/hCDC4-β transcript in specific cell lines from various tumor tissues." (PMID 21122106, 2010). "Collectively, FBXW7 acts as a tumor suppressor in ESCC by promoting the degradation of both SPT6 and ΔNp63, and the SPT6-ΔNp63 axis may serve as a therapeutic target for ESCC." (PMID 41799933, 2026). "Although its tumor suppressor role in many types of cancers has been established, whether and how FBXW7 regulates in vivo esophageal tumorigenesis was previously unknown." (PMID 41799933, 2026). "Although eventual loss of Ctnnb1-mutant transformants was observed in mice rescued at 30 days after ENU treatment, mice rescued at 10 days had an increased tumour burden compared with that observed with initial Fbxw7 priming (mean 62 versus 53 tumours per mouse)." (PMID 41339549, 2026). "Similarly, RPAP2 depletion completely reversed the tumor growth promotion by FBXW7 knockdown, as evidenced by the decreased tumor volume and weight." (PMID 39932049, 2025). "Additionally, Fbxw7 exhibits immunomodulatory effects that restrict effector T cell adaptability and endurance within the tumor microenvironment by inhibiting Notch signaling." (PMID 40901482, 2025). "A mechanistic exploration revealed that FBP1 increases FBXW7 protein levels by inhibiting the auto-ubiquitination of FBXW7, which promotes mTOR ubiquitination to inhibit mTOR levels, thereby inhibiting glycolysis and enhancing the anti-tumor effects of radiation." (PMID 40100307, 2025). "The mechanism by which FBXW7 functions as a tumor suppressor differs among cancer types." (PMID 39823500, 2025). "Consistently, IHC staining of xenograft tumor tissues revealed that the knockdown of RPAP2 rescued the growth‐promoting effect of FBXW7 deprivation, as reflected by decreased staining of Ki67, a marker of cell proliferation, and increased staining of Cleaved‐Caspase‐3, a marker of apoptosis." (PMID 39932049, 2025). "The SCF ubiquitin ligase substrate recognition subunit F-box/WD repeat-containing protein 7, FBXW7, is a well-known tumour suppressor, initiating the ubiquitination and subsequent degradation of many cell cycle-regulated proteins, including oncogenes such as CCNE1(cyclin E), MYC and RICTOR." (PMID 40276932, 2025). "FBXW7 has been widely studied for its significant tumor-suppressive role in various cancers." (PMID 39781455, 2025). "Mechanistically, circIMP3_288aa was found to modulate alternative splicing of FBXW7, a well-known tumor suppressor, suggesting that circIMP3 may drive tumor progression by altering post-transcriptional regulatory networks." (PMID 41561631, 2025).
tumor (continued). "Additionally, we identified AURKA inhibitors as potential therapeutic option for tumours with alterations in tumour suppressors like FBXW7 or NSD1." (PMID 40775769, 2025). "ENKUR may be a tumor suppressor via recruiting FBXW7 to directly ubiquitinate and degrade CTNNB1 in EC." (PMID 39990660, 2025). "Notably, FBXW7, a well-established tumor suppressor gene, downregulates HSF1 expression upon overexpression, indicating that FBXW7 acts as a tumor suppressor in PCa cells by negatively regulating HSF1." (PMID 41154598, 2025). "This analysis led to discovery that AURKA inhibitors may be effective in cancers where tumour suppressors like FBXW7 or NSD1 are compromised." (PMID 40775769, 2025). "However, as a key E3 ubiquitinated protein ligase, the significance of FBXW7 in tumor metabolic reprogramming has been overlooked." (PMID 39823500, 2025). "FBXW7 further regulates the tumor immune microenvironment by targeting C/EBPδ for degradation." (PMID 40534867, 2025). "Similarly, PHF1 regulates FBXW7 transcription by negatively affecting the expression of both the FBXW7 protein and E-cadherin, which promotes tumor proliferation and invasion." (PMID 39749199, 2024). "Conversely, KRAS (p = 2.67e−90), FBXW7 (p = 1.29e−14), BRAF (p = 9.32e−8), GNAS (p = 2.54e−29), and SMAD2 (p = 3.93e−5) mutated tumors were significantly more common in MSLN high expressing tumor samples versus MSLN low expressing tumor samples." (PMID 39174744, 2024). "Patients with HCC have a worse prognosis and a more aggressive tumor when FBXW7 expression is lost." (PMID 39749199, 2024). "Given that most FBXW7 substrates are well-characterized oncoproteins, FBXW7 may serve as a putative tumor suppressor." (PMID 38268032, 2024). "Notably, while FBXW7 is known to be a tumor suppressor, β-TrCP can function as either an oncogene or a tumor suppressor." (PMID 38622197, 2024). "Notably, FBXW7 knockout in tumor cells leads to increased epithelial-mesenchymal transition (EMT), enhanced stem cell properties, and greater migratory potential." (PMID 39749199, 2024). "Similarly, MiRNAs such as MiR-182, MiR-25, and MiR-32 inhibit FBXW7 expression in various cancers, facilitating tumor growth and migration." (PMID 39749199, 2024). "Moreover, FBXW7 suppresses tumor aggressiveness by degrading other substrates, such as Enhancer of zeste homolog 2 (EZH2)." (PMID 39749199, 2024). "In addition, FBXW7 acts as a tumor suppressor by controlling proteasome-mediated degradation of many oncoproteins such as cyclin E, Mcl-1, Jun, Notch, and AURKA." (PMID 39727990, 2024). "Furthermore, FBXW7, identified as a tumor suppressor, interacts with Mcl‐1, prompting the ubiquitination and degradation of this Bcl‐2 family member, thereby inducing apoptosis in cancer cells." (PMID 39329019, 2024). "FBXW7 has been shown to play a crucial role in promoting anti-tumor immunity." (PMID 36998461, 2023). "In addition, the strategy of silencing FBXW7, a recognized tumor suppressor, can break the dormant state of CSCs." (PMID 38027013, 2023). "F‐box and WD repeat domain containing 7 (FBXW7) acts as a critical tumor suppressor." (PMID 37249289, 2023). "In addition, therapies that inactivate FBXW7 and allow tumor stem cells to enter the cell cycle should be considered with caution." (PMID 38027013, 2023). "FBXW7 is frequently absent or mutated in cancer causing the upregulation of a range of tumour promoting oncogenes such as c-MYC." (PMID 37183425, 2023).
tumor (continued). "In a number of human cancers, FBXW7 acts as a tumor suppressor." (PMID 37635248, 2023). "Another way to restore FBXW7 expression involves targeting the FBXW7-microRNA axis in tumor cells." (PMID 38027013, 2023). "Most FBXW7 substrates are promoters of cell growth, including c-MYC, NOTCH, cyclin E, c-JUN, KLF5, and mTOR; therefore, FBXW7 may serve as a tumor suppressor." (PMID 37208442, 2023). "In addition to this, FBXW7 can regulate the tumor immune microenvironment by mediating the degradation of GSK-3β phosphorylated C/EBPδ, influencing macrophage polarization toward M2-type and modulating macrophage innate immune responses." (PMID 38027013, 2023). "In addition, we discuss the potential clinical applications of targeting FBXW7 in the treatment of tumor resistance." (PMID 38027013, 2023). "Their research showed that FBXW7γ acts as a tumor suppressor and might be the only FBXW7 transcript that is related to prognosis in this particular type of cancer." (PMID 37408248, 2023). "Additionally, inactivating FBXW7 leads to a drop in double-stranded RNA (dsRNA) in mice tumor cells, triggering an altered immune microenvironment and anti-PD-1 resistance." (PMID 37658431, 2023). "However, the upregulation of FBXW7-185aa in tumor cells can suppress proliferation, and as a result, GBM tissues have been shown to have lower levels of circFBXW7 and FBXW7-185aa expression relative to adjacent tissues." (PMID 37122733, 2023). "FBXW7 participates in different molecular axes, resulting in different effects on tumor cells." (PMID 37628602, 2023). "Moreover, the genistein treatment significantly inhibited miR-223 expression and upregulated the F-box and WD repeat domain-containing 7 (Fbw7) proteins which act as a tumor suppressor gene." (PMID 38004113, 2023). "Obviously, FBXW7 is an important tumor suppressor E3 ubiquitin ligase." (PMID 38174069, 2023). "FBXW7 is considered a tumor suppressor that diminishes CC cell proliferation and invasion." (PMID 37438760, 2023). "In another study focusing on the association between lncRNAs and miR-182 in CC progression, it was found that LINC00173 lncRNA exhibits a tumor suppressor role and induces the expression of another member of the F-box protein family, FBXW7, by sponging miR-182." (PMID 37438760, 2023). "miR-27a-3p targets FBXW7, leading to its downregulation and promoting tumor growth." (PMID 37408248, 2023). "In this research, the function of FBXW7 was proved in tumor cell lines and xenograft tumor model." (PMID 37249289, 2023). "F‐box and WD repeat domain containing 7 (FBXW7) is a critical tumor suppressor." (PMID 37249289, 2023). "Numerous studies have indicated that FBXW7 often demonstrates abnormalities in various human cancers and may influence tumor biology as well as the development of drug resistance." (PMID 38027013, 2023). "FBXW7 targets several critical regulators of proliferation, tumor growth, and apoptosis." (PMID 37958341, 2023). "Overall, these studies suggest that FBXW7 could play a potential role as a prognostic marker and serve as a tumor suppressor for the development of novel and effective therapies for GC patients." (PMID 37408248, 2023). "FBXW7 was downregulated in tumor spheres compared to their adherent cells." (PMID 36159747, 2022). "For example, FBXW7 (F-box and WD repeat domain-containing 7) could act as a tumor-suppressor targeting various carcinogenic proteins for degradation." (PMID 35197975, 2022).
tumor (continued). "FBXW7’s role as a tumor suppressor has been pervasively explored." (PMID 35515121, 2022). "Fbw7 is a tumor suppressor and tumors often contain mutations in FBXW7, the gene that encodes Fbw7." (PMID 35225231, 2022). "MiR-92a was previously confirmed to be significantly up-regulated in various cancers and to contribute to tumor progression by targeting the FBXW7 protein, which is a critical tumor suppressor and one of the most important molecules involved in the ubiquitin–proteasome system." (PMID 36499093, 2022). "Finally, miR-367, an indicator of a poorer prognosis in NSCLC patients, stimulates tumor growth through direct inhibition of FBXW7." (PMID 35346215, 2022). "Another route to restore FBXW7 expression may be to target FBXW7-microRNAs in tumor cells that harbor wild-type FBXW7 mRNA." (PMID 35346215, 2022). "Furthermore, FBXO9 exerts a tumor-promoting effect in HCC by downregulating FBXW7, thereby increasing the protein levels of FBXW7 oncogenic substrates, such as mTOR." (PMID 35847937, 2022). "To date, only a few studies have shown that FBXW7 interferes with the regulation of CSCs or tumor initiation cells, such as colorectal CSCs, gastric CSCs, and non-small-cell lung CSCs, and has a negative correlation with clinical recurrence and chemotherapy resistance." (PMID 36159747, 2022). "FBXW7 is the most widely researched F-box protein for its tumor suppression role up to now." (PMID 35814468, 2022). "Furthermore, FBXW7 is a component of the ubiquitin ligase complex, which eliminates proto-oncogene products by degradation, acting as a tumor suppressor, and Fbxw7 disruption promotes intestinal carcinogenesis." (PMID 35883434, 2022). "Loss of FBXW7 has been associated with a reduced ability of cells to activate double strand RNA (dsRNA) and interferon (IFN) responses normally activated in cells infected with tumor RNA viruses." (PMID 35346215, 2022). "Notably, FBXW7 expression level was lower in OC tissues than that of normal tissues adjacent to tumor." (PMID 35965327, 2022). "Expression of FBXW7 is negatively correlated with the tumor malignancy of human cancers." (PMID 35064102, 2022). "Knockdown of circ-FBXW7 promotes the malignant phenotype of tumor cells." (PMID 35595755, 2022). "We first determined the mRNA expression status of FBXW7 and p73 in PCa tumors to understand their clinical significance as tumor suppressors using TCGA PRAD dataset (n = 623) analysis, which confirmed their loss of expression in PCa tumors compared to normal prostate tissues." (PMID 35612714, 2022). "However, there is still a lack of elaborate exploration of the contribution of FBXW family members, especially FBXW1 and FBXW7, in various tumor types." (PMID 36591289, 2022). "In tumor number 1006, a deletion was found in the exon region of FBXW7." (PMID 35343095, 2022). "Second, the delivery of drugs may bring out side effects on cancer cells aside from CSCs, such as alterations of proliferation, apoptosis, invasion, and metastasis based on our general concept of FBXW7 as a tumor suppressor." (PMID 35515121, 2022). "It was reported that PLK2 promotes tumor growth by targeting the FBXW7/ Cyclin E pathway." (PMID 35840978, 2022). "Notedly, FBXW7, as a tumor suppressor, was highly expressed in six cancers (CHOL, KIRC, KIRP, LIHC, LUAD and THCA) which may be one of the reasons affecting the outcome of these cancers." (PMID 36591289, 2022).
tumor (continued). "It is well known that the tumor suppressor functions of FBXW7 attributed to its proteolytic regulation of oncogenic substrates such as cyclin E, Yap, c-Myc and Notch, and likely unknown substrates as well." (PMID 35094292, 2022). "The predominantly metastatic tumours in our cohort contained more frequent mutations in several genes such as SETD2, APC, KDM5C, HIF1A, RBM10, TRAK1 and FBXW7, while we detected lower mutation rates in VHL compared to the primary tumours analysed in the TCGA study." (PMID 35231161, 2022). "Furthermore, there were two genes (FBXW7, RET) mutated exclusively in tumours and eight (BLM, GJB2, NOTCH2, NOTCH3, NTRK1, POLE, SOS1, TSC2) solely in metastases." (PMID 34572946, 2021). "We also demonstrated the tumor suppressor role of FBXW7 in group 3 MB." (PMID 33494392, 2021). "Notably, the NOTCH‐mediated activation of miR‐223 transcription has been found to represses the tumor‐suppressive effects of FBXW7 in T‐ALL cell lines." (PMID 33822486, 2021). "F-box and WD repeat domain-containing 7 (FBW7) is a tumor inhibiting protein that can inhibit the emergence and development of numerous types of tumors by regulating the cycle, differentiation, apoptosis, proliferation, invasion, and migration of tumor cells." (PMID 33546236, 2021). "Furthermore, FBXW7α is ubiquitously expressed in a range of proliferating cells and tumor types and is capable of performing almost all the known functions of FBXW7." (PMID 33822486, 2021). "FBXW7 is a potent tumour suppressor which is also involved in maintaining normal haematopoiesis." (PMID 33580200, 2021). "FBXW7 is a well‐studied F‐box protein and is a tumor suppressor." (PMID 33822486, 2021). "Additionally, exosomal miR-92a-3p derived from colorectal CAF targets anti-tumor F-box/WD repeat-containing protein 7 (FBXW7) and a modulator of apoptosis 1 (MOAP1), thereby endowing chemoresistance to cancer cells." (PMID 34760886, 2021). "Furthermore, the decrease in FBXW7 transcriptional activity was found to promote tumor angiogenesis, observed through enhanced expression of angiogenic driver proteins, including NOTCH1." (PMID 33822486, 2021). "Many studies have shown that Fbxw7 is a tumor suppressor by targeting c-Myc, Notch, MCL1 and c-Jun." (PMID 35069531, 2021). "In addition, deubiquitinating enzyme (DUB) USP9X antagonizes Fbxw7 ubiquitylation to regulate Fbw7 protein stability, reduces c-Myc and alleviates tumor progression." (PMID 34658888, 2021). "Our study collectively reported a novel epigenetic mechanism and compelling evidence that METTL3 may enhance the translational efficiency and tumor suppressor function of FBXW7 via a multi-step process involving mRNA m6A methylation." (PMID 33676554, 2021). "Considering the strong functional interconnection between DUB USP28 and E3-ligase FBXW7, the genetic status of FBXW7 may be important to clarify the role of USP28 as an oncoprotein or tumor suppressor." (PMID 34685632, 2021). "FBXW7 is a critical tumor suppressor, which controls the proteasome-mediated degradation of mTOR27." (PMID 34075047, 2021). "FBXW7 functions as an E3 ubiquitin ligase to mediate oncoprotein degradation via the ubiquitin-proteasome system in cancer cells, effectively inhibiting the growth and survival of tumor cells." (PMID 33260160, 2020). "This also suggests that FBXW7 may affect tumor growth and metastasis through different mechanisms via macrophages." (PMID 33260160, 2020). "Since FBXW7 plays an integral role in macrophage function, we hypothesized that it might regulate macrophage phenotype switching in the tumor microenvironment." (PMID 33260160, 2020). "Therefore, FBXW7 suppresses tumor cell survival and proliferation, effectively limiting cancer development." (PMID 33260160, 2020). "Moreover, FBXW7 has been identified as a tumor suppressor gene in several cancers and an FBXW7 knockdown was shown to sensitize cancer cells to chemotherapy." (PMID 32577098, 2020).